CCL2 (C-C motif chemokine ligand 2)
Diseases named in the same sentence as CCL2 in open-access papers (continued):
Sharing a sentence is not in itself a finding about the gene and the disease.
tumor (continued). "In CHLA-255-Fluc mice, combination therapy with anti-CCL2 antibody and etoposide led to a significant decrease in tumor burden compared to the PBS control group (p = 0.02) and the anti-CCL2 antibody alone group (p = 0.05), but not compared to the etoposide alone group." (PMID 37964011, 2023). "This suggests that CCL2 may play multiple opposing roles during different stages of tumour development and progression." (PMID 37108548, 2023). "The results showed that co‐culturing with THP1 Mφ strongly increased CCL2 expression in tumor cells, and this elevation could be restricted under the treatment of IL‐1RA." (PMID 37009412, 2023). "In addition, IFNγ-driven increased expression of chemokines in tumors of Dox-treated mice, such as CCL2, CCL3, CCL5, and CXCL16 has been associated with enhanced recruitment of CD8+ T cells to tumors and reduced tumor progression." (PMID 37478172, 2023). "Indeed, besides CCL2, there are many other chemokines and cytokines involved in the recruitment and accumulation of monocytes/MDSCs and TAMs at the tumor site." (PMID 36845555, 2023). "Furthermore, compared with tumor-bearing WT mice, Mettl3-cKO mice indicated a significantly higher secretion of CCL2 in peritoneal lavage and peripheral blood and CXCL2 in only peritoneal lavage but not in peripheral blood." (PMID 37932814, 2023). "The role of CCL2 may be dependent on the level of CCL2 production by tumours on surrounding tissues." (PMID 37108548, 2023). "Thus, tumor cell-derived GM-CSF was dispensable for the overall production of CCL2 in the 4T1 model." (PMID 37208442, 2023). "However, the mice co-injected with tumor cells and CCL2 KO MSCs exhibited anti-tumor effects when compared with those given tumor cell alone and with control MSCs, partly due to increased infiltration of CD45+CD11b+Ly6G− mononuclear myeloid cells." (PMID 36672395, 2023). "Cytokine analysis of tumor spheroid culture media also showed that treatment with anti-CSF-1R Ab or CSF1R/CCR2/TGF-β Ab resulted in reduced release of monocyte chemoattractant proteins CCL2 and CCL7 by 231 TFM spheroids." (PMID 38076998, 2023). "Despite the role of CCL2 in recruiting both cytotoxic T cells (CTL) and monocytes to tumor sites, studies have shown that enhancement of the CCL2/CCR2 axis or inhibition of CCL2 nitration in antitumor therapy significantly promotes T-cell infiltration and exerts antitumor effects." (PMID 36674931, 2023). "Thus, the CCL2/CCR2 axis appeared to play a dual role by promoting early tumor development (pro-tumor) but sustaining the growth and lung metastasis of BC cells (antitumor)." (PMID 37208442, 2023). "Although the precise timing and process of this remain unknown, the bulk of TAMs are typically produced from blood monocytes, and tumor monocytes recruited via chemokines like CCL2 enter the tumor to develop into TAMs." (PMID 36825088, 2023). "CCL2 is a small chemokine which is mainly produced by tumor cells and surrounding stromal cells." (PMID 36816959, 2023). "Thus, the loss of CCL2 or CCR2 in the host resulted in decreased MDSC recruitment and tumor growth but increased lung metastases." (PMID 37208442, 2023). "The balance of different cell types recruited to the tumour site by CCL2 may determine the rate of tumour growth and progression." (PMID 37108548, 2023). "Following their mobilization from the bone marrow and entry into the bloodstream, MDSC are recruited into tumor tissues in part by following chemokine gradients such as CCL2 and CXCL8, and other cytokines secreted by tumor cells and immune cells within the TME." (PMID 37114134, 2023). "In addition, a previous study supported this by demonstrating that CCL2‐neutralising antibodies inhibited tumour growth in mouse models by suppressing CCL2 gene expression." (PMID 37170733, 2023).
tumor (continued). "CCL2 released by tumor cells, endothelial cells, fibroblasts, and Schwann cells through engaging with its receptor CCR2 is able to regulate the infiltration and migration of tumor-associated macrophages, which facilitate tumor growth by inducing immune suppression." (PMID 37404751, 2023). "In addition, primary PDGFB-driven tumor cells increase CCL2 expression in response to recombinant IL-1β (rIL-1β)." (PMID 37733448, 2023). "In addition, suppression of CCR2 expression in tumor cells normalized tumor growth in EC-Gαs KO animals, indicating that tumor cells are the main effector of endothelial CCL2." (PMID 36374225, 2023). "Moreover, FAM171B enhances CCL2 mRNA splicing by interacting with HNRNPU, ultimately resulted in the recruitment of tumor-associated macrophages (TAMs) and their polarization towards the M2 phenotype." (PMID 37915048, 2023). "MCP-1/CCL2 is associated with increased recruitment of pro-tumorigenic macrophages to TME in multiple cancers and is similarly believed to play an important role in immune cell trafficking to the tumor site in UM." (PMID 37509362, 2023). "Moreover, IL-6 in turn increased the EIF4A3 and CCL2 level within tumor cells in a positive feedback manner, further enhancing tumor cSERPINE2 biogenesis and promoting the recruitment of TAMs." (PMID 36797769, 2023). "Thus, the OC cells with IL-17RA activation released more CCL2 to attract macrophages into the tumor environment." (PMID 37067414, 2023). "In addition to the pro-angiogenic effect, we found that adrenomedullin also suppressed the formation of endothelial CCL2 through cAMP-PKA, and thereby resulted in the suppression of CCL2-induced inhibition of adrenomedullin formation by tumor cells." (PMID 36374225, 2023). "Similar to TRAMP-C1, the parental TRAMP-C2 may exhibit an anti-inflammatory TME that influences the functions of the MSCs (WT and CCL2 KO), supporting mononuclear population and anti-tumor effects." (PMID 36672395, 2023). "In addition, we show that adrenomedullin inhibits the formation of the endothelial angiocrine factor CCL2 which, in turn, can suppress adrenomedullin formation by tumor cells." (PMID 36374225, 2023). "Our results, combined with the literature, support the notion that CCL2 may be a driver of mammographic density and early tumour development." (PMID 37108548, 2023). "Interestingly, CCL-2 expression appeared decreased in tumor tissue compared to normal breast tissue." (PMID 36890825, 2023). "The CCL2/CCR2 axis plays a crucial role in the recruitment of monocytic cells to the tumor site." (PMID 37849753, 2023). "In summary, the MC/OSCC interaction influences tumor cell characteristics, and CCL2 could be identified as a possible mediator." (PMID 36835050, 2023). "In addition, GM1-stimulated macrophages secrete monocyte chemoattractant protein-1 (MCP-1/CCL2) promoting tumor growth and angiogenesis." (PMID 37266839, 2023). "Furthermore, CCL2 mRNA and CCL2 protein expression in brain-seeking tumor cells were inhibited by the NF-κB inhibitor pyrrolidine dithiocarbamate (PDTC)." (PMID 37208442, 2023). "Dihydroisotanshinone I could inhibit tumor migration and cell motility, block macrophage recruitment by lung cancer cells, reduce CCL2 secretion, and suppress p-STAT3 signaling in NSCLC A549 and H460 cells." (PMID 36986550, 2023). "Macrophage infiltration in small‐cell lung cancer was significantly reduced because the epigenetic‐dependent silencing of chemokine (C‐C motif) ligand 2 (CCL2) in tumor cells impeded the recruitment of macrophages derived from blood monocytes into tumor tissue." (PMID 36599655, 2023). "ROS also initiated the inflammatory reaction by the NF-κB pathway to secrete chemokines both in tumor cells and the tumor microenvironment, such as CCL2, CCL3, CXCL2, and CXCl12, which were upregulated by Se-PC PDT, and CCL24 and CXC17, which were downregulated by Se-PC PDT in the tumor niche." (PMID 37994159, 2023).
tumor (continued). "While chronic inflammation promotes tumor progression, tumor cells themselves also attract immune cells via chemokines such as IL-8, CCL2 (MCP-1), CCL3 (MIP-1α), CCL5 (RANTES), CXCL6 (huGCP-2), and cytokines such as IL-1β, IL-6, TNFα, GM-CSF, and G-CSF, inducing inflammation." (PMID 36614196, 2023). "Furthermore, IL-6 in turn increased the EIF4A3 and CCL2 levels within tumor cells in a positive feedback mechanism, further enhancing tumor cSERPINE2 biogenesis and promoting the recruitment of TAMs." (PMID 36797769, 2023). "In addition, NLK regulates phosphorylation and O-GlcNAcylation of STAT3 by binding to STAT3, thereby inhibiting CCL2 expression, in which it inhibits macrophage recruitment in the tumor microenvironment (TME)." (PMID 38008713, 2023). "CC chemokine ligand 2 (CCL2) is a chemokine closely related to tumor." (PMID 38180104, 2023). "However, the CCL2 targeting MAB carlumab was unable to affect the CCL2/CCR2 axis sufficiently or have a single agent anti-tumour effect." (PMID 37033972, 2023). "In addition, TIF1-γ-induced CCL2 upregulation through the CCR2-CCL2 axis recruited macrophages into the tumor, promoting angiogenesis through VEGF-A excretion (Graphical abstract)." (PMID 36357631, 2023). "Furthermore, inhibition of NF‐κB by BAY11‐7085 blocked the IL‐1β‐induced CCL2 secretion from tumor cells in different types of cancer cells." (PMID 37009412, 2023). "However, we have also found an increased expression of different monocyte chemoattractants (e.g., CCL2, M-CSF, CCL5, CXCL12, VEGF) in association with a significantly higher recruitment of tumor-promoting monocytes in the MCS." (PMID 36900330, 2023). "CCL2 is a potent pro-inflammatory chemokine that serves as a chemoattractant for myeloid cells and has been extensively studied as a predictor and potential driver of tumor cell growth and metastasis." (PMID 36599909, 2023). "Moreover, tumor ECs use CCL2, macrophage costimulatory factor (M-CSF), and VEGF to support their growth and the development of metastasis." (PMID 37111629, 2023). "This indicates that CCL2 secreted by tumor cells after treatment with 8 mg/kg of smTRAIL may also contribute to M2b polarization in vivo." (PMID 37605148, 2023). "Moreover, it has been noted that CCL2 levels are related to tumor stage, suggesting that macrophages play an important role in cancer progression." (PMID 36776840, 2023). "In addition, MSCs can also be recruited by CCL2; thus, a local milieu consisting of tumor cells, MSCs, and TAMs can promote tumor progression via a CCL2-dependent paracrine." (PMID 36672395, 2023). "The overexpression of CCL2 is more likely to form a tumor immunosuppressive microenvironment." (PMID 36794651, 2023). "CCL2 has also been shown to promote tumor progression by acting on endothelial cells to stimulate tumor cell extravasation and metastasis or by a direct effect on tumor growth." (PMID 36374225, 2023). "This protein significantly increased Ccl2 mRNA levels after incubation with tumor cells." (PMID 37605148, 2023). "YAP/TAZ-high tumors also secrete CCL2 and recruit TAMs to the tumor microenvironment, which then produce IL6 and GM-CSF to further amplify the accumulation of MDSCs and inhibit the activity of CD8+ T cells from generating an immunosuppressive tumor microenvironment." (PMID 37444578, 2023). "Polarized TAMs can also upregulate CCL2 to induce tumor cell migration." (PMID 37705736, 2023). "In line with our hypothesis, CCL2 neutralization almost completely abolished the effect of HDM on tumor development and progression." (PMID 36670473, 2023). "Finally, exosomal miRNA-155 from tumor-adipocyte crosstalk can upregulate the release of CCL2 and CCL5 from adipocytes, thereby recruiting macrophages around adipocytes and repolarizing macrophages toward the M2-like phenotype." (PMID 36593475, 2023).
tumor (continued). "Moreover, following treatment with chemo- or radiotherapy, cancer cells release inflammatory molecules, including the chemokine CCL2 that further recruits macrophages and promotes tumor proliferation and vascularization." (PMID 37444617, 2023). "Similarly, senescent fibroblasts in colorectal cancer have been shown to release SASP factors, HGF, MIF, and CCL2, which through the activation of Wnt signaling can increase the tumor cell stemness." (PMID 38275386, 2023). "Moreover, the movement of the tumor cells in the increasing CCL2 concentration gradient is abolished with the addition of anti-CCL2 antibody." (PMID 37964011, 2023). "The colony-stimulating factor-1 (CSF1) and chemokine (C-C motif) ligand 2 (CCL2) are two major promoters for macrophage recruitment in the TME, while hypoxia can also induce the production of CSF1 and CCL2 by tumor cells, leading to the downregulation of the corresponding receptors." (PMID 37445721, 2023). "In addition, intratumoral production of peroxynitrite can lead to nitration of the CCL2 chemokine, limiting T cell trafficking within the tumor and resulting in trapping of the cytotoxic T lymphocytes in the stroma surrounding cancer cells." (PMID 36594465, 2023). "The proportion of circulating monocytes was the same in tumor-free WT, Ccl2-/-, or Ccr2-/- mice." (PMID 37208442, 2023). "For example, increased levels of the adipocyte‐related hormone, resistin, the pro‐inflammatory cytokine, IL‐6, and the CC chemokine, CCL2, within the TME of AA women gives rise to an increased density of M2 macrophages, also known as tumor‐associated macrophages." (PMID 36632988, 2023). "In addition, inhibiting the exosomes miRNA-155 of tumor cells can reduce the levels of CCL2 and CCL5 in CAAs co-culture thereby inhibiting tumor growth." (PMID 37666813, 2023). "This study showed that tumor-derived MYBL2 transcriptionally activated CCL2 and recruited M2-like macrophages within clinical tumor tissues and model mice, and thus structured the immunosuppressive OVC microenvironment and attenuated the response to anti-PD-1 therapy." (PMID 37865750, 2023). "Many cells in TME were reported to secrete CCL2, such as monocytes, tumor cells, and stromal cells." (PMID 37654704, 2023). "Genetic deficiency of CCL2 in mouse models of GBM resulted in extended survival of tumor-bearing mice, but did not result in a significant reduction of macrophage presence in tumors." (PMID 36594465, 2023). "Patients with high expression of atypical chemokine receptor 2 (ACKR2) may bind and internalize CCL2 for intracellular degradation to limit tumor metastasis, thus leading to low recruitment of CCR2+ monocytes along with high recruitment of CCR2+ NK cells." (PMID 36880535, 2023). "Backcrossing PyMT/CCL2 mice onto a C57B6 background could reduce the rate of tumour development in the model and enable further examination of the tumorigenesis pathways affected by CCL2 overexpression." (PMID 37108548, 2023). "We cannot neglect to mention that TGF-β induces the secretion of monocyte chemoattractant protein-1 (MCP-1), upregulating the expression of mesenchymal markers and chemotactic factors (CCL-2, 7, 8, 13), which are associated with tumor progression and immunosuppression." (PMID 38006033, 2023). "Among the CCL2 inhibitors, immunomodulatory drugs (IMiDs), which include pomalidomide (NCT03257631), affect various molecular and cellular elements within the TME, and also the levels of various tumor-supporting cytokines, including CCL2, thus modulating monocytes, T cells and NK cells." (PMID 36968588, 2023). "Besides, enhanced adrenergic signaling mobilizes tumor cells to secrete monocyte/macrophage chemotactic factor CCL2, which increases CD14+/CD68+ macrophage infiltration in the TME." (PMID 36707854, 2023). "CCL2-decorated EVs directly targeted CCR2 receptor expressed on the membrane of tumor associated macrophages and promotes lymphangiogenesis through inducing VEGF-C section by tumor associated macrophages." (PMID 36971125, 2023).
tumor (continued). "Among which PC-derived CCL2 can also improve tumor cell survival and tumor growth by stimulating MEK1-ERK1/2-Rho-associated coiled spiral protein kinase 2 (ROCK2)-dependent signaling in tumor cells." (PMID 37666813, 2023). "The tumor size was smaller when giving anti-CCL2 i.t. compared to i.p. in TNC+ tumors." (PMID 37176074, 2023). "Similarly, suppressing CCL2 can prevent M2 recruitment and tumor stem cell renewal, slowing the development of TNBC." (PMID 37895012, 2023). "In regard to MDSCs, FAP+ CAFs releasing CCL2 is recognized by the CCL2 receptor that expressed on circulating MDSCs, leading to the poly-morphonuclear MDSCs infiltration or circulating MDSCs recruitment into the tumor microenvironment." (PMID 37166418, 2023). "MDSCs are generated in the bone marrow and their recruitment to the tumor site is dependent on diverse set of chemokines, such as CCL2, CCL3 and CCL4, for the recruitment of M-MDSCs via the C-C chemokine receptor 2 (CCR2) and the ligands of the CXC-chemokine receptor 2 (CXCR2) for PMN-MDSC." (PMID 37370739, 2023). "Following administration, OVs modulate the tumor microenvironment by attracting bone marrow-derived macrophages and brain resident microglia to the OV-injected tumor site through the release of chemoattractants by OV-infected tumor cells, such as CCL2 and CCN1." (PMID 37234776, 2023). "C-C Motif Chemokine Ligand 2 (CCL2) or C-X-C Motif Chemokine Ligand 8 (CXCL8) could promote tumor proliferation and invasion in an autocrine and paracrine manner." (PMID 37895310, 2023). "Tumor-associated macrophages (TAMs), which are the most abundant population of immune cells in human MPM, largely stems from monocytes recruited by chemotactic factors like CCL2, which is produced abundantly by mesothelial cells exposed to asbestos." (PMID 36900330, 2023). "Similarly, Carlumab (NCT01204996), a monoclonal antibody against CCL2, displayed transitory effectiveness against tumor." (PMID 38035101, 2023). "Since the CCL2 KO MSCs showed enhanced anti-tumor effects compared to WT MSCs in mice injected with either TRAMP-C2 or its derived TRAMP-C2/Luc-eGFP cells, we proposed a working model depicting the potential therapeutic benefit of this genetically engineered cell therapy." (PMID 36672395, 2023). "Similarly, the up-released IL1β by TAMs activates the p38 MAPK signaling pathway and expression of CCL2 by tumor cells." (PMID 37012233, 2023). "However, this study also reported that CCL2 null mutant mice exhibited an increased metastatic spread, and that treatment with anti-CCL2 antibody during early tumorigenesis resulted in a spike in tumour growth." (PMID 37108548, 2023). "Mondini and colleagues confirmed that radiotherapy can promote the secretion of CCL2 by tumor cells and induce the accumulation of CCR2+ Tregs and CCR2-dependent macrophages which can produce TNF-α, then TNF-α induces Tregs activation and decreases the efficacy of radiotherapy." (PMID 36845095, 2023). "Moreover, VEGF production is greatly increased when TAMs are stimulated with CSF-1 or CCL2, inducing increased angiogenesis when these two cytokines/chemokines are present in large amounts within the tumor." (PMID 37143666, 2023). "To test whether CCL2 inhibits adrenomedullin formation in tumor cells, we incubated different tumor cells with CCL2." (PMID 36374225, 2023). "Various levels (high to undetectable) of CCL2 were detected in the tumor epithelium." (PMID 37208442, 2023). "It has been described that CCL2 is able to trigger tumor inflammation." (PMID 36835050, 2023). "Moreover, CCL2 has been described as a “tumor-derived chemotactic factor” since it has been found frequently overexpressed in both neoplastic cells and tumor microenvironment stromal cells." (PMID 37760903, 2023). "Also known as MCP-1, CCL2 plays an important role in tumor growth and macrophage recruitment in the setting of a number of malignancies." (PMID 37153567, 2023).